SMAD2 (SMAD family member 2)
Diseases named in the same sentence as SMAD2 in open-access papers (continued):
Sharing a sentence is not in itself a finding about the gene and the disease.
liver fibrosis (continued). "Galunisertib (LY2157299), an oral inhibitor of TGFβRI kinase, inhibited the phosphorylation of Smad2/3 in a liver fibrosis model, thereby suppressing the production and maturation of COL1A1." (PMID 31614978, 2019). "In hepatitis C virus infection, lncRNA-ATB is activated by transforming growth factor-beta (TGF-β) and competes with miR-425-5p, upregulating the TGF-β type II receptor (TGF-βRII) and SMAD family member 2 (SMAD2), promoting liver fibrosis." (PMID 30781588, 2019). "The expressions of p-Smad2/3 and Smad4 were markedly increased in hepatic fibrosis mice compared with normal mice (p < 0.05)." (PMID 30103395, 2018). "It is widely acknowledged that TGF-β1 is the most potent cytokine fostering hepatic fibrosis; through Smad2 and Smad3 phosphorylation, it activates HSCs to produce collagen III and FN." (PMID 29402324, 2018). "The inhibition of TGF-β1 through both Smad2 and Smad3 significantly ameliorated liver fibrosis in several fibrotic animal models." (PMID 29743985, 2018). "The abrogation of TGF-β1 signaling through both Smad2 and Smad3 has been verified to be able to decrease liver fibrosis." (PMID 29743985, 2018). "Our study demonstrated that Cpd861 can attenuate hepatic fibrosis and its effects on liver function by decreasing Smad2 and Smad3 protein levels while increasing SnoN protein levels." (PMID 29402324, 2018). "Inhibiting the phosphorylation and its expression in Smad2/3 also indirectly leads to downstream signaling inhibition preventing the activation of HSCs and reducing liver fibrosis." (PMID 28594374, 2017). "Activation of HSC by TGF-β plays a key role in liver fibrosis at the early phase and the activated cells are accompanied with high accumulation of p-Smad2/3 and Smad4 in cell nucleus." (PMID 28384213, 2017). "The role of Smad-2 in liver fibrosis is less well characterized but in comparison with Smad-3 seems to regulate a distinct set of target genes." (PMID 27239252, 2016). "APE treatment (5.2 g/kg) significantly decreased Smad2 and Smad3 phosphorylation in liver tissue of rats with hepatic fibrosis (P<0.05)." (PMID 25373883, 2015). "It was recently shown that the expression of the phosphorylated Smad2 and Smad3 proteins was higher in samples of CCl4-induced liver fibrosis, compared with that in the controls." (PMID 25435153, 2015). "Importantly, Gdf10-expressing AAV treatment inhibited the SMAD2-mediated liver fibrosis pathway in the HFFC diet-induced MASH model." (PMID 41281741, 2025). "Furthermore, the downregulation of TGFβ1-induced Smad2/3 activation attenuated liver fibrosis and decreased morbidity and mortality among patients with chronic liver inflammation." (PMID 38654054, 2024). "In addition, we also provided evidence showing that LRRC1 regulates HSC activation by stabilizing phospho-Smad2/3, thereby promoting the development of liver fibrosis." (PMID 38473980, 2024). "Furthermore, LRRC1 promoted HSC activation and liver fibrosis mainly by enhancing the stability of p-Smad2/3 via ubiquitination, thereby contributing to the activity of the TGF-β1/Smad pathway." (PMID 38473980, 2024). "Moreover, miR-12135 improved CDAHFD-induced liver fibrosis accompanied with the suppression of CDAHFD-induced upregulation of phosphorylated SMAD2/3 and JNK levels in the activated hepatic stellate cells." (PMID 38235326, 2024). "Specifically, it is suggested that the activation of SMAD2/3 plays a role in liver fibrosis." (PMID 38385079, 2024). "At the same time, miR-488-5p could mitigate liver fibrosis in vivo through inhibiting TGF-β/SMAD2/3 pathway." (PMID 36001230, 2023). "Numerous studies have revealed that TGF-β/SMAD2/3 signaling pathway is closely related to HSCs activation and fibrogenesis, for example, piperine inhibited HSCs activation and mitigated hepatic fibrosis via activating Nrf2 which sequentially repressed TGF-β/SMAD2/3 signaling pathway." (PMID 36001230, 2023).
liver fibrosis (continued). "Both TGF-beta and SMAD2/4 have a well-recognized role in heart fibrosis; likewise, miR-338-3p and let-7a regulate cardiac fibrosis and hypertrophy, while miR-182 has a role in pulmonary and liver fibrosis." (PMID 37947656, 2023). "The results showed that TLR3 deficiency caused severe clonorchiasis with increased parasite burden, exacerbated proinflammatory cytokine expression and liver lesions, promoted the TGF-β1/Smad2/3 pathway and myofibroblast activation, exacerbated liver fibrosis (compared to WT mice)." (PMID 37167198, 2023). "The p-Smad2/3 was investigated to explore whether indirubin could alleviate the TGF-β/Smad signaling pathway in mice after CCl4-induced liver fibrosis." (PMID 37605732, 2023). "Furthermore, TPLR inhibited TGF-β/Smad pathway ameliorating hepatic fibrosis though downregulation the expression of Smad2/3, Smad4, and upregulation the expression of Smad7 in vivo and in vitro." (PMID 36829153, 2023). "Natural products inhibit liver fibrosis by inhibiting SMAD2/3." (PMID 37686810, 2023). "However, another study showed that SIRT6 alleviated liver fibrosis by deacetylating and inactivating SMAD2 in hepatic stellate cells of an experimental liver fibrosis model." (PMID 37777567, 2023). "Transforming growth factor-beta (TGF-β) is a fibrogenic cytokine activated by the HSC activation and binds to their receptors on cell surface and starts the activation of other transcription factors such as Smad2, collagen alpha 1, and myofibroblasts, thereby promoting hepatic fibrosis." (PMID 35784733, 2022). "The present study also investigated in detail at whether PZH had an impact on the expression of TGF-β1 and its downstream key transduction factor Smad2 during CCl4-induced liver fibrosis." (PMID 36188553, 2022). "Moreover, decreased CCAT2 diminished liver fibrosis through preventing phosphorylated Smad2/3, Smad4 and TGF-β1 signaling." (PMID 36482069, 2022). "MSC transplantation could attenuate liver fibrosis by down-regulation of TGF-β1, Smad2, collagen type I, and smooth muscle alpha-actin (αSMA), reducing liver fibrosis regions in vivo." (PMID 35527304, 2022). "Collectively, GZFL could reduce CCl4-induced liver fibrosis in vivo by inhibiting TGF-β1/Smad2/3, CUGBP1 signaling and activating IFN-γ/STAT1/Smad7 signaling." (PMID 35387552, 2022). "This may be due to the overexpression of SMAD family member 2 (SMAD2) that is closely related to the development of liver fibrosis." (PMID 36388166, 2022). "GZFL could inhibit acetaldehyde‐induced cellular fibrosis and alleviate CCL4‐induced liver fibrosis by inhibiting TGF-β1/Smad2/3, CUGBP1 signaling and activating IFN-γ/STAT1/Smad7 signaling." (PMID 35387552, 2022). "Besides, it was reported that the natural product kaempferol attenuates hepatic fibrosis by reducing collagen synthesis, suppressing HSCs activation and inhibiting Smad2/3 phosphorylation." (PMID 35791909, 2022). "A study found that mice HSC could dysregulate the expression of microRNA 18 A through the PERK pathway of ERS and induce the overexpression of mothers against decapentaplegic homolog 2 (Smad2) to promote liver fibrosis." (PMID 36535923, 2022). "We also showed that Antrodin C could attenuate CCl4-induced liver fibrosis in mice through blocking phosphorylation of Smad2/Akt/ERK/P38." (PMID 35242813, 2022). "Moreover, we further verified the role of membrane receptor Robo2 and its downstream PI3K/Akt and Smad2/3 signalling pathways in sTREM‐1‐related liver fibrosis in vivo." (PMID 34750987, 2021). "Moreover, TGF-β signaling induces liver fibrosis through the sequential activation of downstream mediators including Smad2 and Smad3." (PMID 34772443, 2021). "Similarly, PPARα activation also inhibits hepatic fibrosis by suppressing Smad2/3 phosphorylation via inhibiting the expression of α-SMA and collagen." (PMID 34938805, 2021). "For example, the lncRNA LFAR1 promotes liver fibrosis by enhancing Smad2/3 phosphorylation." (PMID 33664479, 2021).
liver fibrosis (continued). "The downstream proteins, namely Smad2 and Smad3, are activated by phosphorylation, which further promotes the transcription of genes encoding ECM components, then accelerates the development of liver fibrosis." (PMID 32943114, 2020). "Additionally, as little as 50 mg/kg of HD is sufficient to alleviate liver fibrosis from several causes, including the inhibition of NF-κB/IL-1β/IL-10 and TGF-β/Smad2/3/CTGF signaling pathway and prevention of HSC activation." (PMID 32863858, 2020). "Our study found that miR-98 could suppress HLF expression in HSCs and attenuate liver fibrosis by inhibiting the HIF-1α/TGF-β/Smad2/3 axis." (PMID 32637414, 2020). "To investigate the underlying mechanism of the effect of hFSSC secretome on liver fibrosis, we performed the Western blot and RT-qPCR to analyze the expression of TGF-β1, Smad2, Smad3, Smad7, and Collagen I in HSCs, as it is one of the major effector cells in liver fibrosis." (PMID 32883340, 2020). "Therapeutic agents inhibiting pro-fibrotic TGF-β1/Smad2/3 signaling could prevent renal fibrosis 94, liver fibrosis 95, 96, pulmonary fibrosis 97, 98, and cardiac fibrosis 99-101." (PMID 31929736, 2020). "The number of hepatic crown-like structure, which was macrophage aggregation and related to liver fibrosis, was drastically increased and fibrosis area was also increased through upregulating immunoexpression of Phosphorylated Smad2 (key signaling molecule of TGF-β1) and Galectin-3." (PMID 32139740, 2020). "Collectively, our study demonstrates that miR-98 suppress HSCs activation by targeting HLF directly and interacting with HIF-1α/TGF-β/Smad2/3 signaling pathway, which may be an effective therapeutic target for liver fibrosis." (PMID 32637414, 2020). "The development of liver fibrosis depends on the phosphorylation of Smad2/3." (PMID 32365537, 2020). "We also observed that the blocking of Slit2/Robo1 signaling could attenuate phosphorylation of Smad2/3 in a TGF-β-independent way in liver fibrosis." (PMID 31242633, 2019). "In opposite to Smad2/3, Smad7 serves as an inhibitory Smad that could block the activation of TGF-β1 signals via inhibition of Smad2/3, playing a protective role in liver fibrosis." (PMID 29743985, 2018). "The effect of Cpd861 on p-Smad2, p-Smad3, and SnoN expression show that these proteins may be treatment targets for hepatic fibrosis." (PMID 29402324, 2018). "In summary, our data may identify lnc-LFAR1/Smad2/3 nexus as a novel regulator of TGFβ and Notch pathways in liver fibrosis, suggesting that lnc-LFAR1 may be a candidate anti-fibrotic target." (PMID 28747678, 2017). "Thus, Smad2/3 mediated expression of type I collagen A1 in activated HSCs and targeted deletion of Smad2/3 prevented or halted the progression of hepatic fibrosis in animals." (PMID 26758514, 2016). "Furthermore, induction of TGF-β1 increased the α-smooth muscle actin (α-SMA), p-Smad2/3, hydroxyproline and collagen 1A2 (Col 1A2) levels in the liver, suggesting a significant liver fibrosis." (PMID 17949486, 2007). "After 8 weeks of liver fibrosis in mice, the expression level of smurf-2 in the liver was decreased and the level of Smad2 was up-regulated, which also proved from the side that the Smurf-2 protein of hybrid bream in this experiment may be regulated by Smurf-2." (PMID 39062724, 2024). "Furthermore, curcumin was found to inhibit liver fibrosis in rats by a mechanism that may be related to enhanced ubiquitination and proteasomal degradation of SMAD2 by SMURF2." (PMID 37777567, 2023). "However, Smad2 and Smad3 have a similar structure and are intensely activated in liver fibrosis, whereas Smad3 directly binds to DNA sequences that regulate a series of fibrogenic (collagen) target genes and markers (α-SMA and E-cadherin), which belongs to Smad3-dependent genes." (PMID 34307359, 2021). "Thus, we deduced that Fstl1 neutralizing antibody could attenuate CCl4-induced liver fibrosis in mice through blocking phosphorylation of Smad2/JNK." (PMID 32933544, 2020).
liver fibrosis (continued). "Western blotting showed that the ratio of phosphorylated Smad2 (pSmad2) to total Smad2 was greatly increased in CCl4-induced fibrotic livers, whereas immunization with HBcΔCTGF138–159 significantly abolished this increase along with inhibiting hepatic fibrosis." (PMID 27562139, 2016). "TGF-β1 could be involved in liver fibrosis in a Smad2-dependent manner during Sj infection." (PMID 26199461, 2015). "In addition, TGF-β1/Smad2 and Smad3 signal pathway was also the main pathway which could be regulated in liver fibrosis." (PMID 24860243, 2014). "Collectively, miR-125a-5p negatively regulates HSC activation in liver fibrosis, exerting its anti-fibrotic activities through suppressing the TGF-β/Smad2/3 pathway and autophagy modulation." (PMID 40890107, 2025). "In the present study, after DMDD treatment, hepatic TGF-β, Smad2, and Smad3 were significantly downregulated, and COL1A1, α-SMA, and TIMP1 were key genes in liver fibrosis." (PMID 40453659, 2025). "PZW alleviated hepatic fibrosis in vivo, primarily by inhibiting collagen accumulation through navigating IL-6/JAK2/STAT3 and TGF-β/Smad2/3 signaling pathways." (PMID 41293246, 2025). "In summary, autocrine GDF10 activates BMPR2/ALK3‐SMAD1/5/8‐SMAD7 pathway to counteract the TGF‐β‐SMAD2/3 pathway in HSCs, thereby inhibiting HSC activation and preventing liver fibrosis." (PMID 40125634, 2025). "Additionally, research by Peng Qi indicated that GDF-15 plays a profibrotic role in liver fibrosis in mice via the TGF-β/Smad2/3 pathway, proposing that inhibiting GDF-15 may serve as a viable treatment approach for alleviating fibrosis and delaying HSC activation." (PMID 41333917, 2025). "This study identifies autocrine GDF10 activates BMPR2/ALK3‐SMAD1/5/8‐SMAD7 pathway to counteract the TGF‐β‐SMAD2/3 pathway in HSCs, thereby inhibiting HSC activation and preventing liver fibrosis." (PMID 40125634, 2025). "MEL has been reported to have potent antifibrotic effects in terms of both renal fibrosis and hepatic fibrosis and anti-EMT effects that are mediated by the TGF-β1/Smad2/3 pathway." (PMID 39968084, 2025). "In a previous study, we proposed that J2H-1702 can ameliorate liver fibrosis by inhibiting pro-fibrotic gene expression and TGF-β1-mediated collagen synthesis, α-SMA production, and Smad2/3 phosphorylation in a fibrotic environment." (PMID 40118823, 2025). "In cardiac and hepatic fibrosis, Slit2/Robo1 signaling significantly upregulates TGF-β1 expression and activates the downstream expression of SMAD2/3." (PMID 39768930, 2024). "SMAD2, SMAD3, SMAD4, and SMAD7 expression levels were measured to determine TGF-β1 related hepatic fibrosis." (PMID 39055873, 2024). "Quantitative real-time polymerase chain reaction (qRT-PCR) elucidated the downregulation of key hepatic fibrosis markers (ACTA2, COL1A1, and SMAD2) upon exposure to crude KL extract." (PMID 39062514, 2024). "Our research group previously also substantiated that sTREM-1/Robo2 strengthened HSCs activation and the occurrence of hepatic fibrosis through PI3K/Akt and Smad2/3 signaling pathways." (PMID 38297025, 2024). "At the same time, phosphorylated Smad2/Smad3 positively feeds back into the TGF-β pathway, exacerbating the development of liver fibrosis." (PMID 37056286, 2023). "The Western blotting further confirmed that the DDC diet stimulates the release of TGF-β1 to activate the phosphorylation of SMAD2/3, which leads to P-SMAD2/3 translocation from the cytoplasm to the nucleus and induces HSC activation and liver fibrosis." (PMID 37446187, 2023). "In a bile duct ligation animal model of liver fibrosis, Tß4 reduced the expression of many molecules important in the fibrotic pathway including TGF-ß1 (Transforming growth factor-ß1), TGF-ß RII, Smad2, and Smad3." (PMID 36613994, 2022). "All these data suggested that GZFL was able to ameliorate liver fibrosis in vitro and in vivo by modulating the crosstalk between TGF-β1/Smad2/3 and IFN-γ/STAT1/Smad7 signaling pathway via CUGBP1." (PMID 35387552, 2022).